KRAS (KRas proto-oncogene, GTPase)
Diseases named in the same sentence as KRAS in open-access papers (continued):
Sharing a sentence is not in itself a finding about the gene and the disease.
cancer (continued). "Kirsten rat sarcoma (RAS) 2 viral oncogene homolog (KRAS) mutations were reported to drive CRC by promoting cancer progression in activating Wnt/β-catenin and RAS/extracellular signal-regulated kinase (ERK) pathways." (PMID 35203586, 2022). "KRAS mutation coordinates the multifaceted reprogramming of cancer metabolism; therefore, the network of this reprogramming should be elucidated in order to develop novel drugs for KRAS-mutated cancers." (PMID 36291140, 2022). "Although mutations of all three types of RAS members (NRAS, HRAS, and KRAS) can cause cancer, KRAS is the most common oncogene, accounting for 85% of all RAS mutations." (PMID 36080477, 2022). "Oncogenic KRAS mutations are prevalent in human cancers, but effective treatment of KRAS-mutant malignancies remains a major challenge in the clinic." (PMID 35039048, 2022). "The CodeBreak 101 study (ClinicalTrials.gov Identifier: NCT04185883) investigated sotorasib monotherapy and in combination with other anti-cancer treatments in patients with advanced solid tumors with KRAS G12C mutation." (PMID 36012655, 2022). "The PI3K/AKT/mTOR pathway is persistently activated by KRAS mutation, which contributes to cancer progression." (PMID 35517800, 2022). "Predictors contained in candidate prediction nomogram included age, CEA, vascular invasion, T stage, N stage, family history of cancer, and KRAS mutation." (PMID 35279173, 2022). "One of the most frequently mutated oncogenes in human cancers is KRAS, which has been considered an undruggable target for decades." (PMID 35806187, 2022). "Specifically targeting and disrupting mutant KRAS alleles through encoding Cas9 by the LVs in KRAS‐mutant cancer cells, cell proliferation was inhibited in vivo." (PMID 37323878, 2022). "The RAS-MAPK pathway is one of the most deregulated and extensively characterized pathways in human cancer, with KRAS being the most frequently mutated gene." (PMID 35158933, 2022). "KRAS mutations are often initiating, being sufficient to induce tumorigenesis in mice and truncal in many human cancers." (PMID 36069770, 2022). "Preclinical studies show that lentiviral delivery Cas9 and guide RNA targeting mutated KRAS significantly inhibits proliferation of cancer cells." (PMID 35189910, 2022). "KRAS-mutated cancers are distinguished by alterations in metabolic pathways including elevated glycolysis and glutaminolysis as well as increased breakdown of fatty acids and nucleotides." (PMID 36048281, 2022). "Pathological analysis of biopsy samples shows malignant tumors of the right pleura, and next-generation sequencing of 26 genes showed a KRAS gene mutation." (PMID 35321429, 2022). "In contrast to the mutual exclusivity of mutations in oncogenes KRAS and BRAF, cancers with PIK3CA mutations have often concomitant mutations in either of these genes of the KRAS/BRAF/MEK/ERK pathway." (PMID 36295658, 2022). "At present, many studies have evaluated the influence of KRAS mutation on the curative effect of ICIs in cancer patients." (PMID 36189266, 2022). "We observed that AR score was positively associated with many malignant pathways in pan-cancer, such as epithelial mesenchymal transition, KRAS signaling up, TGF beta signaling, hypoxia, and so on." (PMID 36479101, 2022). "Thereafter, we investigated the underlying mechanisms by which BCL6 inhibition blocked KRAS-mutant cancer growth." (PMID 36377663, 2022). "Co-occurring PI3K mutations did not influence OS (16.0 vs. 14.2 months, P = .62) or PFS (7.4 vs. 6.8 months, P = .91) for KRAS non-G12R mutated cancers." (PMID 36124727, 2022). "KRAS is mutated in a wide array of human cancers, including PDA, colorectal, NSCLC, endometrial cancers, and cholangiocarcinoma, most of which are aggressive and resistant to conventional antineoplastic therapies." (PMID 35395857, 2022). "KRAS is the most frequently mutated (85% of all RAS-driven cancers), followed by NRAS (12%) and HRAS (3%) (COSMIC v80)." (PMID 35456940, 2022).
cancer (continued). "Among them, mutations of KRAS account for 85% of observed RAS mutations in cancer and the mutation of residue 12 is one of the dominant mutations in KRAS." (PMID 36033504, 2022). "Prior studies have also shown that lung cancer cells harboring KRAS mutations reprograms cancer cell metabolite towards glutamine dependence through NRF2-mediated signaling activities that increase expression of enzymes involved in glutaminolysis." (PMID 35626147, 2022). "The KRAS gene, which is found on chromosome 12p12.1, is the most frequently mutated oncogene in human malignancies in general, accounting for 22% of all cancers." (PMID 36004014, 2022). "These acquired KRAS mutations include other common variants in KRAS that are seen across mutant KRAS-driven cancers, such as the G13D and G12V substitutions, as well as a novel mutation in residue 96 (KRASY96D) that are yet to be documented in the clinic." (PMID 35147163, 2022). "Nearly all factors of the RAS pathway are altered in cancer, most frequently activating mutations of KRAS, NRAS, HRAS, BRAF and receptor tyrosine kinases (RTKs)." (PMID 35456940, 2022). "Aberrant activation of this pathway is common in several cancers, including CC, which often results from the presence of mutations and amplifications of KRAS." (PMID 35877232, 2022). "In general, KRAS gene mutation at different prevalence rates is associated with a series of highly fatal cancers." (PMID 35305624, 2022). "In another study, 43 patients with KRAS G12C mutated cancers, including 36 NSCLC, were assessed in paired analyses upon progression on sotorasib." (PMID 36284306, 2022). "Presently, although there are fewer studies on human cancers caused by mutations of NRAS than on those induced by mutations of KRAS, it is known that mutationsof NRAS are indeed involved in human tumorigenesis." (PMID 36080363, 2022). "As such, oncogenic KRAS mutations have been linked to programmed cell death 1 ligand 1 (PD-L1) expression in cancer cells of lung or pancreatic origin." (PMID 35965494, 2022). "On the basis of the significant role of KRAS oncogenic mutations, many miRNAs that target KRAS have been discovered in many human cancer tissues." (PMID 34489556, 2022). "Both the T cell pools of healthy individuals and cancer patients contain T cells that can identify KRAS mutation." (PMID 35922812, 2022). "KRAS mutation is a hallmark of cancer and hampers the association of GTPase-activating proteins, which leads to GTP hydrolysis, therefore stabilizing effector binding and stimulating KRAS signaling." (PMID 35563733, 2022). "A mutated driver of many cancers, including pancreatic cancer, is KRAS, which is currently being studied as a target for therapies." (PMID 35740545, 2022). "Here authors show the engineering of T cell engaging bispecific protein able to selectively target cancer cells with a high-frequency mutation in the KRAS oncogene." (PMID 36088370, 2022). "Depletion of ORP5 or ORP8 reduces PtdSer in the PM, causes KRAS mislocalization in vitro, and attenuates KRAS signaling in vivo; in addition, it reduces cell proliferation of KRAS-dependent cancer cells." (PMID 35386193, 2022). "As a result, cancers with KRAS mutation had a higher level of T-cell infiltration than tumors with KRAS wild-type." (PMID 36061356, 2022). "The turn-on mutations of the KRAS gene, coding a small GTPase coupling growth factor signaling, are contributing to nearly 25% of all human cancers, leading to highly malignant tumors with poor outcomes." (PMID 36359850, 2022).
cancer (continued). "It is known that 86% of mutations in the RAS protein, which constitutes mutated RAS proteins in cancer, come from the one most closely related to the KRAS genes." (PMID 35409064, 2022). "Gene set enrichment analysis (GSEA) manifested that cancer hallmark epithelial-mesenchymal transition and KRAS pathways were positively activated in the high-risk group." (PMID 35422861, 2022). "Kirsten rat sarcoma viral oncogene homolog (KRAS) mutations have been identified in several cancers." (PMID 35323350, 2022). "In the United States alone, nearly 150,000 new cases of KRAS-mutated cancers are diagnosed each year across these three cancer types." (PMID 35573474, 2022). "A high prevalence of oncogene KRAS mutations have been frequently observed in a variety of cancers, including human iCCA." (PMID 35305624, 2022). "The enhanced catalytic effect leads to the activation of its structure and disrupts the inactive state of KRAS, causing cancer cells to promote proliferation." (PMID 35631410, 2022). "For example, KRAS mutation only presents in less than 40% of lung cancer patients and in less than 2% of 26 cancer types." (PMID 35053515, 2022). "The decreased sensitivity to MEK inhibition in cancer cells containing oncogenic KRAS mutations is likely due to another RAS-effector pathways (e.g. PI3K pathway) that can maintain cell proliferation and survival." (PMID 35899070, 2022). "Among these oncogenes, KRAS is the best-recognized oncogene with the highest mutation rate in all cancers including highly fatal cancers such as pancreatic ductal adenocarcinoma, non-small-cell lung cancer, and colorectal cancer." (PMID 36613455, 2022). "Among the RAS family, KRAS is widely mutated, with activating mutations in KRAS witnessed in nearly 30% of cancers." (PMID 35163234, 2022). "KRAS mutations at the amino acid location G12 have been associated with more aggressive cancer types and a poorer prognosis." (PMID 36497424, 2022). "Among 19 variables, 7 potential risk factors with nonzero coefficients were identified by LASSO regression analysis, including age, CEA, vascular invasion, T stage, N stage, family history of cancer, and KRAS mutation." (PMID 35279173, 2022). "KRAS is the most frequently mutated oncogene in human cancers, with mutations in about 30% of all cancers, although the prevalence varies greatly in different tumors." (PMID 35359599, 2022). "Inhibition of macropinocytosis promotes a persistent dormant state in the intrinsic KRAS-mutated cancer cell line Sawano." (PMID 36291839, 2022). "KRAS-mutated cancers scavenge extracellular constituents through macropinocytosis in order to meet their adaptation to nutrient stress." (PMID 36291140, 2022). "We used 30 cancer cell lines with different KRAS mutations and multiple in vitro assays to show that both pharmacologic and genetic KRAS inhibition is selectively effective against KRAS-mutant murine and human tumors in vivo." (PMID 35327394, 2022). "Our study confirmed the value of proteogenomic integration in uncovering novel cancer biological implications of oncogenic driver KRAS mutations and further demonstrated the utility of proteogenomics in guiding therapeutic regimens." (PMID 35836817, 2022). "Gradient detection rates of KRAS have been found to be correlated with the levels of KRAS mutation accumulated in different cancer stages, revealing highly detectable KRAS mutation based on DNA-containing sEVs." (PMID 36167539, 2022). "KRAS mutants are common in many cancers and wild-type KRAS is essential in development as its absence causes embryonic lethality." (PMID 36238685, 2022).
cancer (continued). "We tested three cancer cell lines with active KRAS mutations (MDA-MB-231, HCT116, and A549), three cancer cell lines with WT KRAS (MCF7, HT-29, and NCI-H520), and a normal cell line (HME1)." (PMID 35839996, 2022). "They provide insight into the reason why specific cell-types are sensitive to KRAS mutations during cancer initiation." (PMID 36238685, 2022). "Given its non-invasive nature and the resulted high specificity, cfDNA testing represents a promising screening assay for detecting KRAS mutations in cancer patients." (PMID 36386815, 2022). "BRAF V600 class 1 mutations were only observed in i3 cancers and KRAS exon 3 mutations were enriched amongst i3 cancers." (PMID 35773407, 2022). "Despite multiple possible oncogenic mutations in the proto-oncogene KRAS, unique subsets of these mutations are detected in different cancer types." (PMID 36069770, 2022). "In our study, we first established cancer models in the model organism fruit fly by using mutated human gene KRAS, and then we performed both genetic and drug screens to find possible therapeutic targets and drugs for treatment." (PMID 34797366, 2022). "To evaluate how effective KRAS is in single cancer, we calculated p values to analyze the association of clinical data with single cancers." (PMID 36330448, 2022). "Analysis of combined datasets from four leading cancer mutation databases detected KRAS in 19 out of 29 cancer types and was marked as the “Everest” of oncogenes." (PMID 36359850, 2022). "Oncofetal RNA-binding protein (Igf2bp1) is responsible for different types of cancer and can synergize mutation to KRAS." (PMID 35409064, 2022). "In summary, the studies established ARS-853 to be a selective, covalent inhibitor with low micromolar potency in cancer cells harboring G12C mutations in KRAS." (PMID 35045886, 2022). "Although BCL6 depletion led to growth arrest in all tested cell lines, KRAS-mutant cancer cells were more susceptible to BCL6 inhibition than WT cancer cells." (PMID 36377663, 2022). "A variety of cancer entities are driven by KRAS mutations, which remain difficult to target clinically." (PMID 35091677, 2022). "Cancers with common KRAS mutations can be treated with an inhibitor of lysosomal acidification in mice." (PMID 35879364, 2022). "Although KRAS gene mutation is related to metabolic reprogramming in cancer cells or in genetically engineered mouse models, it’s biological effects on metabolic reprogramming in human cells as early events in PDAC carcinogenesis are unclear." (PMID 33833413, 2022). "Clinical data have implicated not only that mutated RAS isoforms vary by tissue and cancer types, but also within the most frequently KRAS-mutations, the mutated amino acid residues of KRAS are also different for each cancer." (PMID 36430338, 2022). "Another study conducted on 46 cancer patients found that KRAS mutations increased the risk of metastasis, recurrence and death." (PMID 36447228, 2022). "Regarding glucose metabolism, KRAS-mutated cancers increase glucose uptake by upregulating glucose transporters in CRC and PDCA." (PMID 36291140, 2022). "Patients with KRAS G12R vs. non-G12R mutated cancers had significantly longer median OS (20.4 vs. 14.3 months, P = .0047) and PFS (12.2 vs. 6.8 months, P = .009)." (PMID 36124727, 2022). "KRAS is mutated in approximately 25% of cancer patients and first KRAS G12C-specific inhibitors showed promising responses." (PMID 36048281, 2022). "GOT1 is involved in coordinating the glycolytic and the oxidative phosphorylation pathways in KRAS-mutated cancer cells." (PMID 36139528, 2022).
cancer (continued). "KRAS is the most frequently mutated oncogene and KRAS signaling functions as a main driver of tumorigenesis and development in various human cancers." (PMID 36338696, 2022). "Somatic mutations that introduce a cysteine residue, such as KRAS p.G12C, that can be covalently targeted by cell-permeable drugs provide an opportunity for simplified antibody recognition of cancer cells." (PMID 36099883, 2022). "PDAC is one of the types of cancer with the lowest survival rates and accumulating evidence indicates that mutations in KRAS are an early event that drives this disease." (PMID 36383067, 2022). "By this criterion, EGFR-mut cancers, consistent with the cohort’s overall decreased mutation rate, have only 10 gene mutations under directional selection compared to 153 and 205 for KRAS-mut and NEK, respectively." (PMID 36612014, 2022). "The aim of this review is to address the most relevant characteristics and differential functions of the KRAS splice variants as they relate to cancer onset and progression." (PMID 36393833, 2022). "As KRAS mutation is also known to drive cancer cell invasion and metastasis, we next tested the invasive ability of the HCT116 cells that lack KRAS mutation (HKH2) or that are resistant to MEK inhibitor treatment (TRAMR) cells." (PMID 34856074, 2022). "Such endogenous TRAIL-dependent TRAIL-R2-mediated activation of the Rac1/PI3K/AKT pathway has been shown to promote migration, invasion and metastasis of KRAS-mutated cancer cells." (PMID 36158196, 2022). "Mutation sites of the KRAS gene have to be considered to be an effective way to develop new cancer treatment schemes." (PMID 36330448, 2022). "Two examples are the mRNA-5671 developed by Moderna/Merck and partners for cancers involving KRAS Mutations and the drug BNT113 developed by BioNTech for HPV-16-caused cancers." (PMID 35892709, 2022). "Despite an appreciation that different KRAS mutations can manifest in quantitative or qualitative signaling differences, how each contributes to the mutational patterns of this oncogene in cancer is unclear." (PMID 36069770, 2022). "KRAS mutations have been reported in many types of cancer, including pancreatic, lung, colon, breast, and GC." (PMID 35444235, 2022). "The remaining pathways MYC targets, angiogenesis, Wnt/β-catenin signaling and KRAS signaling are associated with cancer." (PMID 36009267, 2022). "KRAS is the most frequently mutated oncogene; mutations are found in ∼14% of all cancers, with particularly high frequency in pancreatic and colorectal cancers." (PMID 36088370, 2022). "For instance, cancer cells harboring KRAS mutations have been shown to reprogram cancer cell metabolism towards an increase in uptake and catabolism of amino acids, such as glutamine and tryptophan, with pro-tumoral effects." (PMID 35626147, 2022). "The association between cancer type and KRAS mutational status can be partially explained by tissue-specific differential exposure to mutagens such as tobacco smoke." (PMID 35319967, 2022). "An altered cellular signaling increases the production of ROS as well as activating antioxidant programs, which are advantageous and drive tumorigenesis of KRAS-mutated cancers." (PMID 36359850, 2022). "Among KRAS-driven cancers, pooled analysis of multiple cancers shows that 2.8% of cases exhibit concurrent KRAS mutations." (PMID 36284306, 2022).